CD4 (CD4 molecule)
Diseases named in the same sentence as CD4 in open-access papers (continued):
Sharing a sentence is not in itself a finding about the gene and the disease.
parasitemia (continued). "Low viral load, CD4 count greater than 500, the absence of diarrhea and the ART treatment are not always indicative of free parasitic infection as found in this and other studies." (PMID 34178224, 2021). "The mean CD4+ T lymphocyte counts of HIV uninfected TB patients with and without parasitic infections were 600.53cell/μl and 664.22 cell/μl, respectively." (PMID 32033581, 2020). "On the contrary, when mice were transferred with CD4+CD25+ Treg cells from naïve mice, blood parasitemia showed the same level as control mice (data not shown)." (PMID 23509755, 2013). "To date, no studies have compared the relative contributions from CD4 and CD8 T-cell effector subsets (i.e., TEM versus TEMRA) in protection from asexual parasitemia or clinical infections." (PMID 21935482, 2011). "Eighty five percent of CD4−/− mice and all of the CD8−/− mice failed to develop ECM even though parasitemias were similar to those of WT mice during the first week of infection." (PMID 21494565, 2011). "While there was an increase in CD4+ T cell levels after initiation of treatment among newly diagnosed HIV positives, CD4+ T cell levels and parasitemia (18S copy numbers/μL) were not significantly correlated, somewhat favoring a role for TS versus immune reconstitution." (PMID 36506016, 2022). "Accordingly, depletion of either CD4+ or CD8+ T cells resulted in a significant decrease in IL-10 levels in the lung and full protection from MA-ARDS, without affecting parasitemia." (PMID 35768411, 2022). "Although IFN-γ expression by CD4+ T cells is necessary for decreasing parasitemia, the present result indicated that the secretion of IFN-γ by adoptively transferred CD4+ T cells is not absolutely required for extending the survival time of infected Il18ra-/- recipients." (PMID 35670567, 2022). "In addition, low viral load, CD4 count greater than 500, the absence of diarrhea and the ART treatment are not always indicative of free parasitic infection." (PMID 34178224, 2021). "However, our data demonstrate that CD4+ T cell-derived MCSF does play a nonredundant role in sustaining SCSM abundance and limiting recrudescent parasitemia." (PMID 27923070, 2016). "Furthermore, the selective elimination of MZ macrophages by treating B6 mice with a low dose of clodronate liposomes (ClLip) did not affect the course of parasitemia, IFN-γ production by splenic CD4+ T cells or mouse survival." (PMID 25658925, 2015). "Furthermore, in studies done in children aged 3–6 years who were infected with P. falciparum, lower CD4+ and CD8+ cell counts were observed in those with acute malaria when compared with children with no parasitemia or in those with asymptomatic parasitemia." (PMID 23327493, 2013). "However, when EAE was induced in a group of mice with controlled parasitemia, no amelioration of the clinical signs of EAE was observed, and the percentage of CD4+CD25+ cells was comparable to that in naïve animals." (PMID 21464982, 2011). "Among the 80% of children who had a parasite infection in the preceding 3 months (with or without symptoms), there was a highly significant positive correlation between the frequencies of Pf-specific total IL10 producing CD4 T cells and parasite density during infection (rho = 0.35, p < 0.0001)." (PMID 29097996, 2017). "The CD4+ T cells of the co-infected group increased in number in response to parasitemia prior to SIV inoculation, responded slightly to the subsequent parasitemia following SIV infection just before day 120, and failed to respond to the following parasitemias." (PMID 19774084, 2009).
depression (290 papers, 2004 to 2026). "Previous studies have shown that a decline in CD4 lymphocyte levels is associated with an increased risk of depression in HIV-positive individuals." (PMID 40282923, 2025). "In conclusion, this study illustrates key immune cell subsets implicated with depression and suggests that reduction in CD4+ naive T cells is a reliable predictor of poor antidepressant treatment efficacy." (PMID 38867657, 2024). "We tested for the association between depression, substance use and VL suppression as outcomes, and the exposure to ≥ 3 ACEs controlling for socio-demographic variables and latest CD4 count." (PMID 39507827, 2024). "In contrast, depression, taking Bactrim as prevention treatment that reflects a lower CD4 count and consistent condom use were associated with impaired Sti dimension." (PMID 36662750, 2023). "For example, one previous study shows that mitochondrial fission in mice CD4+ T cells causes anxiety, depression, and other behavioral abnormalities." (PMID 37703110, 2023). "Based on these ranges, we conclude that the absolute number of Tregs is reduced in the setting of HIV-DLBCL, likely owing to the associated depression in overall CD4 T-cell counts." (PMID 36630466, 2023). "The frequencies of CD4+CCR7lowTCM cells, mainly Th1-like cells, were identified to be robustly correlated with MS-associated depression, deepening the understanding of inflammatory characteristics of depression." (PMID 35844577, 2022). "Trans-diagnostic and cis-diagnostic risk variants (for schizophrenia and depression) are enriched at epigenetically active sites in brain tissues and in lymphoid cells, especially stimulated CD4+ T cells." (PMID 36243721, 2022). "As inflammatory RORγt + CD4 + Th17 T cells and their primary cytokine IL-17 have been implicated in the development of stress-induced depression, the connection between stress, the Ahr, Th17s and depression remains critical to understanding mood disorders." (PMID 35597802, 2022). "In our present research, we investigated the pathogenetic effect of CD4+ Th17 cells in the pathogenesis of chronic stress-induced depression and intended to unravel the underlying mechanisms." (PMID 35836182, 2022). "Low level of education and older age, clinical and HIV related variables such as the advanced stage of the illness and CD4 count of 500 cells/dl or less, and comorbidity of depression were associated with HIV associated neurocognitive disorders." (PMID 35711575, 2022). "Patients with depression have lower CD4 or CD8 lymphocyte counts, which are associated with other markers of immune system function, such as interleukins and proinflammatory cytokines." (PMID 35069302, 2021). "Higher percent CD8+ levels during treatment was associated with poorer quality of life and more depression, while higher CD4+ and CD8+ were associated with poorer neuropsychological memory and processing speed performance." (PMID 32434503, 2020). "Immunocompromised condition reflected by low CD4 count and those who are symptomatic were associated depression occurrence compared to those clinically stable and had high CD4 count." (PMID 32742304, 2020). "Secondly, food insecurity is also associated with a significant reduction in CD4 count, which has been consistent, associated with a greater risk of depression in PLWHA in previous studies." (PMID 32571426, 2020). "In a Malawian study of 562 adolescents, self-rated depression severity was also associated with more severe immunosuppression (based on CD4 count)." (PMID 31354539, 2019). "For example, various CD4+ Th cell subsets have been implicated in stress induced depression-like behavior: Percentages of Th17 cells were found to be elevated in brains of mice exhibiting learned helplessness and after chronic restraint stress." (PMID 31319604, 2019). "A preponderance of the patients showed good adherence to their ART, however the minority with poor adherence had associations with depression, anxiety disorder and low CD4 count." (PMID 31692880, 2019).
depression (continued). "These two groups (patients visiting for the first time or patients with a CD4 of 50 or less) can thus be classified as high-risk groups and should be prioritised for evaluation of clinical depression." (PMID 31402989, 2019). "In previous studies, several factors have been found to be associated with depression such as education, income, and CD4 counts." (PMID 30231885, 2018). "This is consistent with other research which found an association between depression and CD4 cell levels." (PMID 29590151, 2018). "Studies in Africa revealed that in PLHIV, depression is also associated with poorer health status overall, including low weight gain, low CD4 progression, suicide but also with faster progression to AIDS and increased mortality." (PMID 28783739, 2017). "In Uganda, most research on depression and HIV focus on people who are already HIV infected, and report an association of depression with lower condom use, higher alcohol use, lower self-efficacy, lower CD4 count, and poorer antiretroviral treatment adherence." (PMID 28103834, 2017). "In multivariate logistic regression, suicidal ideation was significantly associated with being single, female sex, having CD4 level <500, presence of OI, depression, and poor social support." (PMID 27747101, 2016). "A bivariate analysissuggested an association of NCI with gender, age, educational level, depression,current CD4 count and lowest CD4 count." (PMID 27626305, 2016). "Authors found that depression was independently associated with failing to obtain a CD4 count (after being referred for testing by a healthcare provider) (RR = 0 · 82, 0 · 72-0 · 94)." (PMID 24981595, 2014). "Under Bonferroni correction for multiple comparisons (i.e., using significance level 0.05/11 = 0.0045), both alcohol abuse (p = 0.003) and CD4 counts (p < 0.0001) are significantly associated with probable depression." (PMID 24053612, 2013). "As predicted by the HCE Model, scores on the HCE Inventory (HCEI) were linked in expected directions to depression, provider relationships, treatment adherence, and indicators of clinical status such as CD4 and viral load." (PMID 23029184, 2012). "The influence of CD4+CD25+ Treg cells deficiency on CIS-induced development of depression-like behaviors in mice was examined." (PMID 22860054, 2012). "Our findings regarding the association between major depressive disorder and low CD4 counts are in keeping with previous studies." (PMID 23209556, 2012). "A study on 300 HIV-infected men found that older age and depression were associated positively with ED, and higher CD4 cell counts were associated negatively, then, and higher CD4 was considered protective regarding ED." (PMID 22046183, 2011). "CSF HIV RNA correlated neither with the severity of the AIDS dementia complex (ADC) nor abnormal quantitative neurological performance, although these measures were associated with depression of CD4 counts." (PMID 16266436, 2005). "Depression has been associated with lower CD4 in both high‐income and LMIC PWH cohorts." (PMID 40045453, 2025). "Similarly, PLWHIV with a CD4 cell count of less than 200 cells/mm3 display a higher risk of depression do patients with a CD4 count greater than 350 cells/mm3." (PMID 39791692, 2025). "Employment was identified as a preventive factor, whereas having a low CD4 count, recently initiating antiretroviral therapy, and having chronic non-communicable diseases were associated with increased odds of depression among HIV-positive patients on antiretroviral therapy." (PMID 38238489, 2024). "When analyses were adjusted for difficulties in getting around, self-care, social participation, anxiety, depression, stress, current CD4+ T-cell counts, and HIV RNA levels, the associations remained statistically significant for I-FABP levels (p=0.033) and IP-10 levels (p=0.019)." (PMID 39524438, 2024).
depression (continued). "Accounting for ART status and CD4 count closest to the time of TB diagnosis, food insecurity continued to be associated with increased symptoms of depression (adjusted PR = 2·33; 95 % CI 1·24, 4·38) and anxiety (adjusted PR = 1·53; 95 % CI 1·03, 2·26) in the multivariable model." (PMID 33070794, 2022). "I, inorder to confirm that whetherage and CD4+ T cells counts couldinfluencewere associated with anxiety, depression, and sleepmeasures, we analyzed the correlation of age and CD4+ T cells countsfor score of questionnaires." (PMID 36384522, 2022). "We also hypothesise that depressed adolescents will present with increases in percentage of CD4+ T cell when compared with adolescents with low- and high-risk of depression." (PMID 34927102, 2021). "Moreover, follow-ups of larger-sampled work from our group will aim to determine if there are associations between ACE, anxiety, and depression with specific immune cell types, such as CD4+ or CD8+ T cells, M1/M2 macrophages, and specific B cells subtypes." (PMID 34205709, 2021). "However, in addition to greater CD4 cell decline, depression was associated with lower odds of linkage to care within 90 days, overall ART initiation within the study period, and retention in care." (PMID 33490927, 2021). "Depression was associated with linkage to care, missed visits, and CD4 decline." (PMID 33490927, 2021). "Similarly, a study conducted in Uganda showed that CD4 count > 200 was associated with lower occurrence of depression (protective)." (PMID 32742304, 2020). "Similarly a study conducted in Ethiopia Yekatit 12 hospital showed that CD4 count < 250 was associated with depression and similar finding in Cameron showed that CD4 count < 100 was associated with high depression." (PMID 32742304, 2020). "For the active treatment group following treatment (4th assessment), CD4 was negatively correlated with CD4 on QoL total (r = − 0.62, p = 0.010) and Zung depression (r = − 0.51, p = 0.026), in that higher CD4 was associated with poorer QoL and more depression." (PMID 32434503, 2020). "Depression, anxiety disorder and low CD4 count were however associated with poor adherence." (PMID 31692880, 2019). "In addition, depression causes decreased natural killer cell level and activity, faster decline in CD4 count and increased risky sexual behavior that results in contracting additional disease that compromise the immune system." (PMID 30909970, 2019). "Effect of CD4 count and viral loads on the risk of depression (BDI-II)." (PMID 28141867, 2017). "Depression and substance abuse are well recognised causes and consequences of intimate partner violence and have also been associated with a faster rate of decline in CD4 in individuals with HIV." (PMID 25816336, 2015). "However, both HIT and MCT regimens effectively attenuate the HE-induced autographic depression and apoptotic activation of CD4 lymphocyte, which are associated with lowered blood peroxide and Th2 cytokine productions." (PMID 24236174, 2013). "Thus while some work has reported that a low CD4 count is associated with having depression in PLWHA, other researchers have found otherwise." (PMID 23209556, 2012). "The presence of depression in PLWHA could also lead to a decline in CD4 levels; such an association has been previously documented." (PMID 23209556, 2012). "Meanwhile, accumulating evidence suggests that CD4+ T cells may influence susceptibility to depression as well as its treatment outcomes." (PMID 23110234, 2012). "The use of this animal model may further clarify the role of helper T cells and provide insight into the effects of CD4+CD25+ Treg cells on the susceptibility to the induction of depressive disorders." (PMID 22860054, 2012).
depression (continued). "For instance, an emerging literature indicates that selective serotonin reuptake inhibitors (SSRIs) may mediate broader mechanisms, such as inflammatory CD4+ T cell reactivity and vascular/platelet reactivity, which underlie both depression and preeclampsia pathogenesis." (PMID 38384900, 2024). "CD4 count could indirectly be linked to depression and vice versa." (PMID 32818041, 2020). "The odds of depression were significantly higher in individuals with a CD4 cell count below 200 cells/mm3 compared to those with 200 cells/mm3 or more." (PMID 40485941, 2025). "Yoga-based programs lowered anxiety, depression, and fatigue while improving quality of life and, in one pilot, increased CD4 T-cell counts." (PMID 41466226, 2025). "It is also in line with our finding that in Routine-term hospitalization group, pre-treatment depression patients’ CD4+Tn MM was lower than at discharge." (PMID 40756310, 2025). "Measures included sociodemographics (age, sex, race, neighborhood deprivation index [NDI]), duration of HIV status, Charlson Comorbidity Index (CCI), HIV RNA, CD4 cell counts, higher risk tobacco use (TAPS tobacco score ≥ 2), depression, and anxiety symptoms." (PMID 40730987, 2025). "HIV-positive patients who had the most recent CD4 count < 200 cells/mm3 were seven times [AOR = 6.99 (95%CI 2.81–17.38)] more likely to have depression than patients with CD4 count ≥ 500 cells/mm3." (PMID 38238489, 2024). "In humans, low levels of serum CD4 + CD25 + T cells have been observed in patients with major depression." (PMID 38902845, 2024). "HIV-positive patients with the most recent CD4 count ≤ 200 cells/mm3 were seven times more likely to have depression than patients with CD4 count ≥ 500 cells/mm3." (PMID 38238489, 2024). "The input variables were demographic (sex), health-related (depression, CD4), and neuroimaging predictors." (PMID 39518362, 2024). "Our study also showed that monocytes from UC patients with symptoms of anxiety/depression inhibited CD4 + T cells polarized to Treg cells, but induced CD4 + T cells to differentiate into Th1 cells, modulating the immune response." (PMID 36906523, 2023). "A study used multiparameter flow cytometry to identify CD4+CD25+ Tregs and CD4+ CD25+FOXP3+ Tregs in major depressive disorder." (PMID 37238593, 2023). "The odds of depression were 2.50 times higher in study participants with a low CD4 cell count (AOR = 2.50, CI: 1.54–4.06)." (PMID 37908331, 2023). "Compared to healthy controls, patients with depression have been shown to have increased neutrophil, monocyte, neutrophil/lymphocyte, CD4/CD8 cell-ratio, and T helper 17/T regulatory ratios." (PMID 37098514, 2023). "Other factors such as HIV, lower immunity, antiretroviral medication side effects, low CD4 cell count, efavirenz-based ART regimen, duration of living with HIV, stress, anxiety, and depression were all linked to sleep disturbances." (PMID 36864404, 2023). "We intended to determine the crucial role of CD4+ Th17 cells in the development of specific subtypes of depression and unravel the underpinnings of their pathogenetic effect." (PMID 35836182, 2022). "The relationship of CD4+ T cells and their corresponding cytokines with anxiety and depression has been revealed by previous studies." (PMID 36386524, 2022). "HIV RNA viral load, CD4 cell count, fasting total cholesterol (TC), triglyceride, glucose, neuropsychiatric adverse events, depression and QOL were assessed over 48 weeks." (PMID 35001501, 2022). "So it is predictable to have fewer circulating CD4+ T-cells and a reduction in natural killer cell and cytotoxic lymphocyte proliferation responses in elderly patients with clinical depression and stressful states." (PMID 36201406, 2022). "Based on the results of one study, there were more CD4+ T cells and a higher level of IL-6 in the peripheral blood of depression patients." (PMID 35844577, 2022).